IL4 (interleukin 4)
Diseases named in the same sentence as IL4 in open-access papers (continued):
Sharing a sentence is not in itself a finding about the gene and the disease.
Cerebral ischemia (23 papers, 2017 to 2026). Restriction of arterial blood supply to the brain associated with insufficient oxygenation to support the metabolic requirements of the tissue. "In contrast, IL-4 has been associated with protective mechanisms of brain ischemia and can induce anti-inflammatory M2 microglial phenotype expression in primary rat cortical glia cultures and encourage PPARγ-dependent microglial phagocytosis." (PMID 34772945, 2021). "In addition, a deficiency of IL-4 accompanied a lower expression of IL-10, which is an M2 microglia marker and a potent anti-inflammatory cytokine produced by microglia, in a cerebral ischemia–reperfusion animal model." (PMID 36181630, 2023). "Therefore, the regulation of IL-4 or IL-5 and its associated pathways are potential targets for the treatment of cerebral ischemia." (PMID 31164999, 2019). "This is also intriguing in light of studies that have reported that IL-4 can drive an “M2”-like microglial phenotype that was critical for recovery after cerebral ischemia." (PMID 41550504, 2026). "In young mice, the levels of IRF4 and CD206, anti-inflammatory factors such as TGF-β, IL-4, and IL-10, are significantly higher in the brain compared to old mice after cerebral ischemia." (PMID 37361996, 2023). "TNF-α and IL-1β are classical inflammatory cytokines after cerebral ischemia, while IL-4 and IL-10 are anti-inflammatory cytokines." (PMID 35496902, 2022). "Mice lacking IL-4 have more M1-polarized microglia/macrophages, larger infarcts and more severe functional deficits after cerebral ischemia, while recombinant IL-4 can eliminate these effects." (PMID 35173738, 2022). "IL4 KO mice show a worsened neurological outcome and increased brain damage following cerebral ischemia." (PMID 34829993, 2021). "To date, IL-4 has been reported to participate in neuroprotection against cerebral ischemia and that the upregulation of M2 microglia induced by IL-4 treatment has a neuroprotective effect." (PMID 34692788, 2021). "Recent studies also highlighted the effect of IL-4 on long-term behavioral performance after cerebral ischemia." (PMID 34692788, 2021). "Low IL-4 has been shown to enhance excitatory transmission, thereby aggravating cerebral ischemia, and low IL-10 has been shown to exacerbate the inflammatory response after MCAo." (PMID 33924148, 2021). "Injection of IL-4 into C-4BL/6 mice with cerebral ischemia has been found to be effective in improving the spatial memory and learning abilities." (PMID 32778140, 2020). "For instance, in the early stage of cerebral ischemia in ICH rats, local administration of IL-4 was suggested to be associated with a diminished M2 alternative phenotype." (PMID 30669620, 2019). "IL-4 or IL-10 knock-out mice have a worse outcome after cerebral ischemia due to an enhanced expression of M2 markers." (PMID 30584250, 2018). "Additionally, treadmill exercise also improves reperfusion injury in cerebral ischemia by enhancing interleukin 4 (IL-4) expression and promoting M2 microglia activation, potentially through the JAK1-STAT6 pathway." (PMID 40688988, 2025). "After cerebral ischemia, neurons in the penumbral zone rapidly produce IL-4." (PMID 37361996, 2023). "Moreover, treadmill training could relieve cerebral ischemia‐reperfusion injury by facilitating M2 microglia activation through IL‐4 upregulation mediated by the JAK1/STAT6 pathway." (PMID 37143406, 2023). "Activation of NF-κB induces the production of pro-inflammatory cytokines (IL-4, IL-10, IL-13, TGF-β) and adhesion molecules (IL-6, IL-1β and ICAM-1), thus intensifying tissue injury in cerebral ischemia-reperfusion." (PMID 40656619, 2025). "Moreover, the IL-4 knockout after cerebral ischemia might increase brain damage and inflammation." (PMID 34591125, 2021).
Cerebral ischemia (continued). "For instance, HMF showed neuroprotection against brain ischemia by inducing BDNF production and anti-inflammatory actions and demonstrated an immunomodulatory function for the reduction of interleukin-4 expression in CD3/CD28-stimulated spleen cells in mice." (PMID 37180721, 2023).
emphysema (23 papers, 2004 to 2025). "CD8+ T-cells primarily secrete IL-4 and IL-5 cytokines, both of which are implicated in lung parenchymal tissue damage that exacerbates the development of emphysema." (PMID 35350787, 2022). "Type 2 cytokines (e.g., IL-4 and IL-13) promote mucus hypersecretion, airway remodeling, and emphysema by enhancing mucin synthesis, airway mucosal permeability, fibrin deposition, and protease production." (PMID 40589761, 2025). "Pathologically, IL-4– and IL-13–mediated processes align with hallmark COPD features such as airway barrier disruption, mucus plug formation, fibrotic remodeling, and emphysema." (PMID 41024111, 2025). "In recent experimental models, basophils have been identified as having a role in emphysema development through IL-4-mediated generation of MMP-12-producing macrophages." (PMID 38622557, 2024). "The authors concluded that the basophil-derived IL-4/monocyte–derived IM/MMP-12 axis plays a role in emphysema development." (PMID 37205111, 2023). "They suggested that basophil-derived IL-4 promoted the differentiation of infiltrating monocytes into MMP-12–producing IMs that caused the alveolar wall destruction and emphysema formation." (PMID 37205111, 2023). "In this study, CCL-17 was significantly decreased in the emphysema group, whereas IL-13 and IL-4 were elevated." (PMID 36248880, 2022). "The previous study has elucidated that IL-4 produced by basophils induces the differentiation of accumulated monocytes into MMP-12 producing IMs in a mouse model of emphysema induced by elastase." (PMID 34425800, 2021). "IL-4 secreted by activated basophil would induce a shift from lung-infiltrating monocyte to interstitial macrophage and IL-4/macrophage/macrophage-derived MMP-12 axis plays an important role in the development of emphysema." (PMID 34259107, 2021). "The degree of emphysema, concentration of IL-4, IFN-γ and CXCL10, and expression of CXCR3 and CXCL10 in mice administrated with low dose vitamin D3 were similar to the normally treated mice." (PMID 31737787, 2019). "A pulmonary airway model was designed, and morphological assessment of emphysema, IL-4, IFN-γ and CXCL10 concentration in bronchoalveolar lavage fluids, expression of CXCR3 and CXCL10 were detected." (PMID 31737787, 2019). "Synergistically, IL-4 and IL-13 drive M2 macrophage polarization, B cell class-switching, IgE production, mast cell degranulation, epithelial barrier dysfunction, airway hyperresponsiveness, fibrotic remodeling, and emphysema." (PMID 41024111, 2025). "The bronchoalveolar lavage (BAL) interleukin 13 (IL‐13), IL‐4, and IL‐5 levels in the overlap model were higher than in the pulmonary emphysema model and lower than in the type 2 airway inflammation model, but IL‐33 level in the lung was higher than in other models." (PMID 38652015, 2024). "However, a recent study proposed that IMs are the primary MMP-12 producers, and that the IL-4/IM/MMP-12 axis is important for the development of emphysema." (PMID 37592330, 2023). "The reduction of CCL-17 suggests that the reduction of M2 macrophages in emphysema is mainly dominated by the M2a subtype, and the reduction of the M2a subtype in turn stimulates the increase of IL-13 and IL-4, and also leads to a decrease in anti-inflammatory capacity." (PMID 36248880, 2022). "Furthermore, neutralization of IL-4 reduced α-GalCer induced emphysema." (PMID 26811900, 2016). "Furthermore, TSK/+ mice exhibiting disrupted genes encoding IL-4Rα, TGF-β, or IL-4 lacked skin sclerosis but developed emphysema, indicating that different genes are involved in the development of skin sclerosis and pulmonary emphysema in TSK/+ mice." (PMID 17049072, 2006). "Basophil-derived IL-4 enhances the macrophage production of matrix metalloproteinase-12 (MMP-12), accelerating emphysema progression." (PMID 40244222, 2025). "Compared to the emphysema model (ELA), the ACO group was superior in expressing of IL-1β, IL-4, IL-5, IL-6, IL-13, and IFN-γ." (PMID 37511021, 2023).
emphysema (continued). "Administration of anti-IL-4 Abs was found to reduce MMP12 expression and emphysema in α-GalCer administered mice." (PMID 26811900, 2016). "We hypothesized that the IFN-γ and/or IL-4 production by activated iNKT cells enhanced MMP12 expression and the development of emphysema." (PMID 26811900, 2016). "We have previously reported a positive correlation between increase in IFN-γ and IL-10, but not IL-4 or IL-13, responses to EFs from CD4+ T cells isolated from former smokers with emphysema severity." (PMID 22969766, 2012).
leprosy (23 papers, 2009 to 2025). Leprosy is a chronic infectious disease affecting primarily the skin and peripheral nervous system. "IL-10 together with IL-4 is known to be associated with LL pole and MB leprosy while IFN-γ associated with other proinflammatory cytokines and characterized the TT pole and PB leprosy." (PMID 36053342, 2022). "The polymorphism of IRGM rs13361189 was found to be related to leprosy by affecting the production of IL-4, IL-6, and INF-γ." (PMID 29992164, 2018). "In conclusion, our study shows that the NFKβ1 [rs28362491], CASP8 [rs3834129], PAR1 [rs11267092] and IL4 [rs79071878] genes are possible markers for the susceptibility to development of leprosy and the severe clinical form MB." (PMID 26367014, 2015). "Our results indicate that allele A2 is more frequent in leprosy patients compared to healthy individuals, consistent with the fact that higher levels of IL4 would be ineffective in controlling the growth of bacilli." (PMID 26367014, 2015). "Early studies of leprosy intradermal cytokine expression determined that leprosy polarity is associated with TH2 cytokines IL4, IL5, IL10 in lepromatous lesions, and TH1 polar cytokines, IFNG, IL2, in tuberculoid lesions." (PMID 25412496, 2014). "Also in a Chinese population, the 590T/C polymorphism of IL4 was found to be associated with leprosy, which indicated Th2 involvement in leprosy since IL-4 is a typical Th2 cytokine." (PMID 32373110, 2020). "NFKβ1 [rs28362491], CASP8 [rs3834129], PAR1 [rs11267092] and IL4 [rs79071878] genes are potential markers for susceptibility to leprosy development, while the INDELs in NFKβ1, CASP8, PAR1 and CYP19A1 (rs11575899) are potential markers for the severe clinical form MB." (PMID 26367014, 2015). "Detection of Th1 cytokine IFN-γ and Th2 cytokines IL-4 and IL-10 in the PBMCs confirmed Th1/Th2 polarization of immune response in leprosy patients." (PMID 30642265, 2019). "Sandwich ELISA was done in the culture supernatants of healthy and leprosy patients to detect IL-4, IL-10 and IFN-γ." (PMID 30642265, 2019). "Basal mean percentage of IL-4 expressing CD4+ T cells was significantly higher (p = 0.0008) in PBMCs of lepromatous leprosy patients as compared to healthy individuals." (PMID 30642265, 2019). "Notably, IFN-γ counteracted IL-4’s inhibitory effect, indicating the potential for cytokine-based modulation to enhance immune responses in leprosy treatment." (PMID 41306590, 2025). "Patients with co-infections had decreased levels of IFN-γ, a Th1 cytokine, and increased levels of IL-4 and IL-10, Th2 cytokines, suggesting that co-infection might facilitate the development of disseminated leprosy." (PMID 37216331, 2023). "An elevated level of IL-4, IL-6, and IL-8 has also been reported in leprosy." (PMID 37809252, 2023). "Furthermore, Diniz and colleagues reported the decrease of interferon-γ and the increase of Th2 cytokines IL-4 and IL-10 levels in lepromatous leprosy patients co-infected with STH." (PMID 27278453, 2016). "The NFKβ1, CASP8, PAR1 and IL4 INDELs were associated with leprosy susceptibility, while NFKβ1, CASP8, PAR1 and CYP19A1 were associated with the MB (Multibacilary) clinical form of leprosy." (PMID 26367014, 2015). "Interleukin-4 (IL-4) is a key cytokine secreted by Th2 lymphocytes, eosinophils and mast cells that induces the activation and differentiation of B cells and the development of the Th2 subset of lymphocytes, which is ineffective in combating leprosy." (PMID 26367014, 2015). "We investigated the possible effects of CYP19A1 [rs11575899], NFKβ1 [rs28362491], IL1α [rs3783553], CASP8 [rs3834129], UGT1A1 [rs8175347], PAR1 [rs11267092], CYP2E1 [INDEL 96pb] and IL4 [rs79071878] genes in a group of 141 leprosy patients and 180 healthy individuals." (PMID 26367014, 2015). "Additionally, other patients in both types of leprosy also show a non discriminating Th0 cytokine profile with both interferon-γ and IL-4." (PMID 23936569, 2013).
leprosy (continued). "In fact, the role of Th9 lymphocytes in leprosy was evaluated in a study that demonstrated higher levels of IL-9 in the tuberculoid pole, explained by the antagonistic function of IL-9 in relation to IL-4 and IL-10, changing the immune response from the Th2 to the Th1 pole." (PMID 35379512, 2022). "However, many patients in both types of leprosy also show concomitant presence of IL-4 and IFN-γ in antigen stimulated PBMC cultures indicating the presence of non polarized Th0 responses to the pathogen and greater heterogeneity in cytokine producing cells at clonal level." (PMID 23936569, 2013). "Our data demonstrated that leprosy patients presented an overall polyfunctional profile of T-cells subsets, with increased frequency of IFN-γ+ T-cell subsets along with IL-10+ and IL-4+ from CD4+ T-cells." (PMID 33341111, 2020). "Short-term cultures in vitro of peripheral blood mononuclear cells from leprosy patients and healthy Controls were carried out to quantify the percentages of cytokine+ cells (IFN-γ, IL-4 and IL-10) amongst T-cells, CD4+ T-cells and CD8+ T-cells." (PMID 33341111, 2020). "The attribute IL-4+ CD8+ T-cells was a general biomarker to identify both Household contacts, whereas IL-4+ CD4+ T-cells was a general biomarker for both subgroups of Leprosy patients." (PMID 33341111, 2020). "The cytokine signature analysis demonstrated that leprosy patients presented a polyfunctional profile of T-cells subsets, with increased frequency of IFN-γ+ T-cell subsets along with IL-10+ and IL-4+ from CD4+ T-cells, as compared to health Controls (Venn diagram report)." (PMID 33341111, 2020). "For leprosy reactions, the most common proinflammatory mediators were TNF-α (7 articles), IFN-γ (5 articles), IL-6 (4 articles), and IL-17 (3 articles), and the most common anti-inflammatory mediators were IL-4 (4 articles) and IL-10 (4 articles)." (PMID 26339136, 2015). "Recently, it was also observed that dental infections in individuals with leprosy could increase the proinflammatory response mediated by IFN-γ, while the opposite effect occurred for the immunoregulatory activity of IL-4, resulting in exacerbation of the inflammatory reaction." (PMID 26339136, 2015). "However, the finding that some patients of both clinical types of leprosy also showed non polarized Th0 subset with production of both IFN-γ and IL-4 was intriguing and made it difficult to reconcile the leprosy spectrum and anergy based solely on the Th1 and Th2 paradigm." (PMID 24454972, 2014). "In this systematic review, we identified important pro- and anti-inflammatory mediators involved in the occurrence of dental infections and leprosy reactions, including IL-6, IFN-γ, TNF-α, IL-1β, IL-17, IL-10, and IL-4, which were independent of the laboratory technique and sample." (PMID 26339136, 2015).
hepatocellular carcinoma (22 papers, 2009 to 2025). A malignant tumor that arises from hepatocytes. "The polymorphic variant of IL-4 T589C was studied in the context of a possible connection with the development of hepatocellular carcinoma." (PMID 35629280, 2022). "The others studied the association between studied IL-4-590C/T variant and the susceptibility of bladder cancer, hepatocellular cancer, and renal cell carcinoma." (PMID 31871935, 2019). "The results of the analysis showed that the CT genotype of the IL-4 T589C locus polymorphism was significantly more common in the group of patients with hepatocellular carcinoma compared with the group of patients with liver cirrhosis and the group of healthy individuals." (PMID 35629280, 2022). "Transwell and MTT assays demonstrated that the proliferation, migration, and invasion capabilities of liver carcinoma cells were augmented by IL‐4 and IL‐13 contrasted with the DMSO control group, whereas PLX3397 weakened these abilities." (PMID 39268355, 2024). "The same study also demonstrated that IL-4 treatment decreased the amount of HBV DNA in infected hepatocellular carcinoma cells." (PMID 33672018, 2021). "H22 hepatoma bearing mice treated with DCs and DCs stimulated by ESPs showed a decrease in IL-4, IL-6, or IL-10 compared with their levels in the PBS and ESP groups (p < 0.05)." (PMID 32692308, 2020). "PARP14 is involved in normal immune function through the IL-4 signaling pathway and is a prosurvival factor in multiple myeloma and hepatocellular carcinoma." (PMID 30941331, 2019). "Indeed, the IL-4, IL-6, and IL-10 levels were found to be higher in patients with ascites and hepatocellular carcinoma (HCC) than patients with cirrhosis alone." (PMID 40149656, 2025). "Furthermore, c-Jun-mediated JMJD6 repair enhances radioresistance in hepatocellular carcinoma through the IL-4-activated ERK pathway." (PMID 40092686, 2025). "In the serum of patients with hepatocellular carcinoma and supernatants of peripheral monocytes cocultured with Huh7 cells, the levels of cytokines (IL-4, IL-6, and IL-10) could be upregulated, while the level of IFN-γ could be downregulated." (PMID 33435880, 2021). "Our results showed that the production of IL-4, IL-6, and IL-10 in H22 hepatoma bearing mice treated with DCs stimulated by ESPs was significantly reduced, while the expression of IFN-γ was markedly increased, which was the opposite to the cytokine expression in the ESP group." (PMID 32692308, 2020). "Hepatocellular carcinoma (HCC) is a typical inflammation-related cancer, and genetic variations in the IL-4 gene may be associated with the risk of hepatitis B virus (HBV)-related HCC." (PMID 25295591, 2014). "Lan T also reported that in hepatocellular carcinoma KIAA1429 controls the differentiation of T helper 2 (Th2) by inducing separation of RNA binding protein HuR, and so affects the expression of IL-4, IL-5, and IL-13." (PMID 35095993, 2021). "On the other hand, IL-4 induces the differentiation of naïve T cells to Th2, and it has also been shown to suppress HBV replication in hepatocellular carcinoma cell line Hep3B." (PMID 33672018, 2021).